CHKA (choline kinase alpha)
Description:
Plays a key role in phospholipid biosynthesis by catalyzing the phosphorylation of free choline to phosphocholine, the first step in phosphatidylcholine biosynthesis. Also phosphorylates ethanolamine, thereby contributing to phosphatidylethanolamine biosynthesis. Has higher activity with choline. May contribute to tumor cell growth. [Isoform 1]: This isoform plays a key role in lipolysis of lipid droplets following glucose deprivation. In response to glucose deprivation, phosphorylated by AMPK, promoting localization to lipid droplets. Phosphorylation is followed by acetylation by KAT5, leading to dissociation of the homodimer into a monomer. Monomeric CHKA isoform 1 is converted into a tyrosine-protein kinase, which phosphorylates lipid droplet structural proteins PLIN2 and PLIN3, leading to lipolysis of lipid droplets.
Synonyms: CK; EK; CHK; CKI; NEDMIMS
Tractability: Small molecule: a structure with a bound ligand is known; a high-quality ligand is known; it has a high-quality binding pocket. PROTAC: ubiquitination databases record sites on it; its protein half-life has been measured; a small molecule that binds it is known.
Target class: Enzyme; Transferase
Gene: Protein-coding gene on chromosome 11 (68,052,859 to 68,121,444, reverse strand). Ensembl gene ENSG00000110721.
Subcellular location: Cytoplasm, cytosol; Lipid droplet (Isoform 1)
Subcellular location (Human Protein Atlas): Endoplasmic reticulum
Pathways (Reactome):
Metabolism: Synthesis of PC; Synthesis of PE
Gene Ontology:
Molecular function: choline kinase activity; ethanolamine kinase activity; protein homodimerization activity; protein tyrosine kinase activity; identical protein binding
Biological process: phosphatidylcholine biosynthetic process; phosphatidylethanolamine biosynthetic process; CDP-choline pathway; lipid metabolic process; lipid transport
Cellular component: cytosol; lipid droplet; cytoplasm
Genetic constraint (gnomAD): Loss-of-function variants: 17 observed, 27.52 expected, observed/expected ratio (o/e) 0.62, 90% interval 0.42 to 0.93. The upper end of that interval is the gene's LOEUF score, 0.93, which puts it in group 3 of 6, group 1 being the genes least tolerant of losing a copy. Missense variants: 406 observed, 371.84 expected, observed/expected ratio (o/e) 1.09, 90% interval 1.01 to 1.18. Synonymous variants: 163 observed, 146.31 expected, observed/expected ratio (o/e) 1.11, 90% interval 0.98 to 1.27.
Homologues: Orthologues: chimpanzee CHKA (99% identical), macaque CHKA (98% identical), dog CHKA (90% identical), rat Chka (89% identical), pig CHKA (89% identical), mouse Chka (84% identical), guinea pig CHKA (82% identical), zebrafish chka (61% identical), tropical clawed frog chka (53% identical), Caenorhabditis elegans cka-2 (33% identical), Drosophila melanogaster CG2201 (33% identical), Caenorhabditis elegans cka-1 (32% identical), and 4 more. Paralogues in human: CHKB (49% identical), ETNK1 (25% identical), ETNK2 (25% identical).
Diseases named in the same sentence as CHKA in open-access papers:
CHKA is named in the same sentence as 66 diseases in open-access papers, as found by Europe PMC text mining. Sharing a sentence is not in itself a finding about the gene and the disease. The quoted sentences say what the papers report.
breast carcinoma (22 papers, 2009 to 2023). "Overexpression of CHKA and elevated PC and tCho levels of breast cancer cells have been associated with increased invasiveness and drug resistance." (PMID 22277092, 2012). "Furthermore, a combination of CHKA loss and 5-fluorouracil (5-FU) treatment resulted in a larger reduction of cell viability and proliferation in breast cancer cell lines compared to that following 5-FU treatment alone." (PMID 31822964, 2020). "Our study also provides a rationale for testing a CHKA inhibitor in 60% to 70% cases of molecular apocrine-type breast cancers that rely on AR signaling." (PMID 26657335, 2016). "This is in good agreement with the finding that choline kinase alpha, which is overexpressed and activated in human breast cancers, has the ability to use ethanolamine as well as choline as substrates to produce PE and PC, respectively." (PMID 25036036, 2014). "Two cell lines with the highest 18F-D4-FCH uptake, together with detectable CHKA protein expression levels were selected for investigation of the hypoxia-altered choline metabolic phenotypes: including prostate cancer PC-3 and breast cancer MDA-MB-231." (PMID 34452207, 2021). "It has been shown that increased expression of CHKA is critical for proliferation both of mammary epithelial cells and breast cancer, but in vitro studies of different breast cancer cell lines have not conclusively demonstrated a correlation between CHKA expression and PCho concentration." (PMID 20716336, 2010). "Down-regulation of choline kinase alpha (CHKA), the gene regulating the conversion of Choline to PC, has been shown to decrease cell proliferation, and to increase the effect of chemotherapy in ovarian and breast cancers, whereas CHKA overexpression increases drug resistance in breast cancer cells." (PMID 25495193, 2014). "For example, the c-Src-dependent link between CHKA and EGFR promoted breast cancer cell proliferation and tumorigenesis." (PMID 36147318, 2022). "Down-regulation of CHKA expression elicited the endoplasmic reticulum stress and induced apoptosis via CHOP in breast cancer, and it is reported that CHKA could promote glioma development via activating PI3K/AKT pathways." (PMID 36147318, 2022). "In line with this, highly metastatic MDA-MB-231 breast cancer cell line showed impaired migration independent of proliferation and decreased in vivo invasion in zebrafish xenograft assays when CHKA was knocked down." (PMID 34564442, 2021).
lung carcinoma (9 papers, 2011 to 2025). "To further investigate SLC6A8 and CHKA in lung cancer, we analyzed mRNA, protein, and metabolite expression of the two genes in lung cancer cell lines." (PMID 40903981, 2025). "For CHKA, previous studies present contradicting results, for example, indicated its expression was lower, while mentioned it was overexpressed in lung cancer." (PMID 33273919, 2020). "To confirm specificity of CS expression in this context we verified the effect of CHKA inhibition in A549 human lung cancer cells and isogenic cells with depleted mtDNA (A549 Rho)." (PMID 27206796, 2016). "CHKA expression is of prognostic significance in clinical breast and lung cancer, where overexpression correlates with disease progression, poor prognosis and reduced survival." (PMID 27206796, 2016). "Three genes (ALDH3A1, VDR and CHKA) are associated both with ATII physiology and lung cancers." (PMID 21489244, 2011). "CHKA overexpression may play a role in cell proliferation and carcinogenesis, and recent work suggests that high expression of this protein may negatively impact patient prognosis in human lung cancers." (PMID 21489244, 2011). "The silencing of FAM83A can inhibit the proliferation, invasion and migration of lung cancer cells, which may be related to the inhibition of epidermal growth factor receptor (EGFR)/mitogen activated protein kinase (MAPK)/choline kinase α (CHKA) signal transduction and activation." (PMID 37907984, 2023).
ovarian carcinoma (8 papers, 2015 to 2024). A malignant neoplasm originating from the surface ovarian epithelium. "In another study, the downregulation of choline kinase alpha (CHKA) was shown to overcome TRAIL resistance in ovarian cancer cells by specifically increasing the expression of DR5." (PMID 38909249, 2024). "In ovarian cancer, the antioxidant role of CHKA, which is exerted by decreasing glutathione cysteine and methionine content, contributes to sensitizing cancer cells to chemotherapy." (PMID 35740569, 2022). "Choline kinase-α (ChoKα/CHKA) overexpression and hyper-activation sustain altered choline metabolism conferring the cholinic phenotype to epithelial ovarian cancer (OC), the most lethal gynecological tumor." (PMID 33390181, 2021). "Previous studies have demonstrated that expression levels of CHKA could affect proliferation, metastasis, and survival of ovarian cancer and glioma." (PMID 37938654, 2023). "Inhibition of CHKA expression could also overcome resistance to TRAIL-mediated apoptosis in ovarian cancer cells." (PMID 37938654, 2023). "Although the genes in our models do not have obvious mechanisms that might influence drug sensitivity, it is interesting that CHKA in our DOX model has recently been shown to play a role in the sensitivity of human ovarian cancer cells to DOX, paclitaxel, and cisplatin." (PMID 26892349, 2016). "Recently, the inability of CHKA silencing to attenuate MAPK and PI3K/AKT signaling has been observed in ovarian cancer cells." (PMID 27556502, 2016). "Epithelial Ovarian Cancer (EOC) “cholinic phenotype”, characterized by increased intracellular phosphocholine content sustained by over-expression/activity of choline kinase-alpha (ChoKα/CHKA), is a metabolic cellular reprogramming involved in chemoresistance with still unknown mechanisms." (PMID 25796169, 2015).
prostate carcinoma (8 papers, 2009 to 2021). A carcinoma that arises from epithelial cells of the prostate gland. "The association between choline uptake and androgen receptor (AR) expression is suggested by the upregulation of choline kinase-alpha in prostate cancer." (PMID 29138500, 2017). "Tumor xenografts (n = 6 per group) were generated in mice using genetically engineered prostate cancer cells with inducible CHKA knockdown." (PMID 26657335, 2016). "Mining of publicly available Cancer Genome Atlas (TCGA) expression data identified CHKA amplification and/or mRNA upregulation in 11% of breast, 5–10% of lung, 8% of ovarian, 7% of colorectal and 5% of prostate cancers." (PMID 27206796, 2016). "Choline phosphorylation by CHKA has been shown to be upregulated in many cancer types, including breast, lung, colorectal and prostate cancer." (PMID 25888249, 2015). "Increased tCho levels and choline kinase alpha (CHKA) expressions have been detected in prostate cancer cells and xenografts models under hypoxic compared to normoxic conditions." (PMID 22277092, 2012). "Among these, choline kinase alpha (CHKA) expression was evaluated in benign (n = 195), prostatic intraepithelial neoplasia (PIN) (n = 153) and prostate cancer (PCa) lesions (n = 359)." (PMID 26657335, 2016).
colorectal cancer (4 papers, 2016 to 2025). A primary or metastatic malignant neoplasm that affects the colon or rectum. "Aberrant expression of choline kinase alpha (CHKA) has been reported in a variety of human malignancies including colorectal carcinoma (CRC)." (PMID 27556502, 2016). "CHKA is known to be over-expressed in human tumours, while SGK1 regulates survival and growth in colorectal cancers." (PMID 29110037, 2018).
glioma (4 papers, 2008 to 2022). A benign or malignant brain and spinal cord tumor that arises from glial cells (astrocytes, oligodendrocytes, ependymal cells). "The mean z-scores for CHKA and ETNK2 mRNA expression showed a significant reduction in IDHmut glioma samples relative to IDHwt (0.21 in IDHwt to − 0.16 in IDHmut, p < 0.0001 for CHKA and 0.69 in IDHwt to − 0.12 in IDHmut, p < 0.001 for ETNK2)." (PMID 29619216, 2018). "Importantly, CKα (CHKA) mRNA expression is reduced in IDHmut patient biopsies relative to IDHwt in the TCGA low-grade glioma dataset." (PMID 29619216, 2018).
Obesity (3 papers, 2017 to 2025). Accumulation of substantial excess body fat. "Additional studies are needed to determine whether CHKA rs10791957 genotype distribution influences the relationship between diet, obesity and insulin resistance." (PMID 28134761, 2017).
colon carcinoma (2 papers, 2019 to 2020). "ESR2 and CHKA are also associated with colon and esophageal cancers, while CRYGC is only directly related to colon cancer according to the GeneCards database." (PMID 33273919, 2020). "For this reason, we performed in vitro studies in colon cancer cells (SW-620) treated with RE to confirm and validate the specific effect of RE on decreasing the expression levels of JAK1, NFE2L2, CHKA, and BMP2 genes." (PMID 31450563, 2019).
endometrial cancer (2 papers, 2021 to 2022). Primary or metastatic malignant neoplasm involving the endometrium (mucous membrane that lines the endometrial cavity). "Trousil and colleagues found that altered choline metabolism in endometrial cancer is caused by an overexpression of choline kinase alpha and hyperactivation of the deacylation pathway." (PMID 33578729, 2021). "Altered choline phospholipid metabolism in endometrial cancer results from overexpression of choline kinase alpha and an overactivated deacylation pathway." (PMID 36072980, 2022).
epilepsy (2 papers, 2022 to 2025). A brain disorder characterized by episodes of abnormally increased neuronal discharge resulting in transient episodes of sensory or motor neurological dysfunction, or psychic dysfunction. "Rare, biallelic recessive variants in CHKA cause a neurodevelopmental disorder characterized by epilepsy and microcephaly (OMIM #620023) classified as a neurodevelopmental form of complex spastic paraplegia." (PMID 41308990, 2025). "Biallelic variants in CHKA, which encodes the first enzyme in the CDP-choline pathway for the synthesis of phosphatidylcholine, cause an inherited disorder characterized by epilepsy, microcephaly, and intellectual disability." (PMID 41308990, 2025).
lymphoma (2 papers, 2016 to 2022). A malignant (clonal) proliferation of B- lymphocytes or T- lymphocytes which involves the lymph nodes, bone marrow and/or extranodal sites. "CHKA possessed oncogenic activity and could be a potential therapeutic target in lymphoma." (PMID 34983358, 2022).
pancreatic cancers (2 papers, 2021 to 2023). "CHKA was found to be overexpressed in 90% of pancreatic tumors." (PMID 37771441, 2023). "In contrast, gene amplification of CHKA is a recurrent genetic alteration and contributes to CHKα overexpression in a variety of solid tumors, including esophageal, liver, prostate, head and neck, stomach, breast, skin, bladder, uterine and pancreatic cancers." (PMID 34202989, 2021).
colorectal tumors (1 paper, 2013). "Choline kinase alpha (ChoKα), an enzyme that plays a role in cell proliferation and transformation, has been reported overexpressed in many different tumors, including colorectal tumors." (PMID 23762272, 2013).
diabetes (1 paper, 2025). "This study investigates the role of metabolic stress‐induced activation of choline kinase α (CHKA) in endothelial cell (EC) subpopulations, contributing to diabetes‐induced microvascular dysfunction." (PMID 40548950, 2025).
diffuse large B-cell lymphoma (1 paper, 2021). "We found that genetic alterations of CHKA occur at a very low frequency (< 2.3%) in diffuse large B cell lymphoma (DLBCL), pediatric acute lymphoid leukemia (ALL) and chronic lymphocytic leukemia (CLL) and are absent in all other lymphoid malignancies." (PMID 34202989, 2021).
endometrial tumors (1 paper, 2025). "Specifically, aggressive endometrial tumors commonly overexpress choline kinase alpha (CHKA), the enzyme that phosphorylates choline in the first step of the Kennedy pathway." (PMID 40710522, 2025).
endothelial dysfunction (1 paper, 2025). In vascular diseases, endothelial dysfunction is a systemic pathological state of the endothelium (the inner lining of blood vessels) and can be broadly defined as an imbalance between vasodilating and vasoconstricting substances produced by (or acting on) the endothelium. "This study uncovers CHKA as a pivotal driver of vascular dysfunction in diabetic retinopathy and highlights its role in endothelial dysfunction through NAD+‐SIRT1‐Notch signaling." (PMID 40548950, 2025). "Collectively, these findings highlight the endothelial‐specific up‐regulation of CHKA and suggest its potential involvement in endothelial dysfunction and pathological angiogenesis." (PMID 40548950, 2025). "Mechanistically, CHKA regulated endothelial dysfunction through the NAD+‐SIRT1‐Notch signaling." (PMID 40548950, 2025).
Graves disease (1 paper, 2025). Graves' disease is an autoimmune disorder that leads to overactivity of the thyroid gland (hyperthyroidism).It is caused by an abnormal immune system response that causes the thyroid gland to produce too much thyroid hormones. "XIST, PPP1R2C, CALHM6, AL672277.1, TSIX, SHROOM1, ADTRP, JUND, SGK1, CHKA, AO008569.1, MAP7D2, and AIF1 were down-expressed genes in TS compared with both the healthy female and the female patient with Graves’ disease." (PMID 39851522, 2025).
hepatitis C virus infection (1 paper, 2023). A viral infection caused by the hepatitis C virus. "Diseases associated with CHKA (Choline Kinase Alpha) include muscular lipidosis and hepatitis C virus infection." (PMID 37771441, 2023).
Intellectual disability (1 paper, 2025). "In contrast to CHKA disease-causing variants, autosomal recessive variants in CHKB cause a neuromuscular disorder characterized by muscular dystrophy with intellectual disability and cardiomyopathy (OMIM #602541)." (PMID 41308990, 2025).
liver cancer (1 paper, 2016). An epithelial or non-epithelial malignant neoplasm that arises from the liver. "Up to now, the expression of CHKA and its prognostic significance have been demonstrated in lung and liver cancers." (PMID 27556502, 2016).
metastasis (1 paper, 2016). The spread or migration of cancer cells from one part of the body (where they first appeared) to another. "In this study, we found that CHKA was frequently upregulated in CRC clinical samples and CRC-derived cell lines and was significantly correlated with lymph node metastasis (p = 0.028), TNM stage (p = 0.009), disease recurrence (p = 0.004) and death (p < 0.001)." (PMID 27556502, 2016).
metastatic prostate carcinoma (1 paper, 2022). A carcinoma that arises from the prostate gland and has spread to other anatomic sites. "Choline kinase alpha (CHKA), an essential gene in phospholipid metabolism, is among the modulated MALAT1-targeted transcripts in advanced and metastatic prostate cancer (PCa)." (PMID 35740569, 2022).
microcephaly (1 paper, 2025). A congenital or acquired developmental disorder in which the circumference of the head is smaller than normal for the person's age and sex. "This is consistent with the observation that Chka knockout in mice is embryonic lethal, while mice heterozygous for Chka displayed similar brain phenotypes to patients with CHKA, including abnormal white matter and subcortical and connectivity regions, commissural defects and microcephaly." (PMID 41308990, 2025).
muscular dystrophy (1 paper, 2025). Muscular dystrophy (MD) refers to a group of more than 30 genetic diseases characterized by progressive weakness and degeneration of the skeletal muscles that control movement. "The previous observation that AAV-mediated expression of human CHKA in Chkb−/− mice ameliorated the muscular dystrophy phenotype suggests that increased CHKA expression could compensate for loss of CHKB function." (PMID 41308990, 2025).
neuroblastoma (1 paper, 2025). Neuroblastoma (NB) is the most common solid, extracranial childhood tumor. "The association between impaired CHKA activity and elevated lipid peroxidation is further supported by our findings in U2OS bone osteosarcoma cells and SH-SY5Y neuroblastoma cells treated with the CHKA inhibitor EB-3D, which demonstrated a dose-dependent increase in lipid peroxidation." (PMID 41308990, 2025).
proliferative diabetic retinopathy (1 paper, 2025). Advanced retinopathy due to diabetes mellitus characterized by the formation of new vessels in the retina. "To further investigate clinical significance of CHKA in DR, we examined its expression in human proliferative diabetic retinopathy (PDR) samples." (PMID 40548950, 2025).